SULT1E1 (sulfotransferase family 1E member 1)
Diseases named in the same sentence as SULT1E1 in open-access papers (continued):
Sharing a sentence is not in itself a finding about the gene and the disease.
tumor (continued). "In addition to other tumor cell subpopulations, the SULT1E1+ subpopulation may also modulate the activity of immune cells in the tumor." (PMID 36994665, 2023). "Notably, all tumor samples contained cells of MC SULT1E1+ subpopulation." (PMID 36994665, 2023). "Functionally, SULT1E1+ subclones and COL6A3-mediated macrophage-tumor interactions emerged as potential key drivers of malignancy, recurrence, and radioresistance." (PMID 42073533, 2026). "Glucocorticoid receptor expression induced by DEX can also augment SULT1E1 expression in mouse liver and MCF-7 resulting in more E2 sulfation/inactivation and tumor growth inhibition." (PMID 39132498, 2024). "In case of Disease Grade II, surrounding NPSH, MDA and SULT1E1, Tumor NPSH, MDA and SULT1E1 and the percentage of differences of these three parameters are found to be significantly correlated with each other." (PMID 32158360, 2020). "The mRNA expression levels of SULT1A1, SULT1A3, SULT1E1, and SULT2A1 decreased or drastically decreased in 90% of the tumor samples in comparison with the matched pericarcinomatous samples." (PMID 28634336, 2017). "The activities of SULT1A1, SULT1B1, SULT1E1 and SULT2A1 in 9 of 10 samples showed a significant decrease in tumor tissues relative to matched pericarcinomatous tissues, whereas the activities of SULT1A3 in 7 of 10 samples increased." (PMID 28634336, 2017). "Elevated E2 level in the tumor suggest that SULT1E1 expression is not sufficiently enough for E2 inactivation." (PMID 32158360, 2020). "When surrounding SULT1E1 is compared to that in tumor tissue a highly significant and positive correlation is noticed (p < 0.005)." (PMID 32158360, 2020). "Thus, using probe substrates, we systematically measured the metabolic functions of SULT1A1, SULT1A3, SULT1B1, SULT1E1, and SULT2A1 in tumor S9 (tHLS9-pooled), pericarcinomatous S9 (nHLS9-pooled), and reference pooled normal human S9 (rHLS9-pooled)." (PMID 28634336, 2017). "SULT1E1 protein levels were very low in all but one tumor sample (T53) thus it was not possible to accurately estimate differences in protein levels between control compared to EC tissue." (PMID 28690541, 2017). "Sulfate conjugation by other SULT enzymes (SULT1A3, SULT1E1 and SULT1B1) may result in the activation or inactivation of anti-cancer drugs (e.g., raloxifene, sesamol, fulvestrant, and resveratrol), thereby affecting their anti-tumor effects." (PMID 28634336, 2017). "Contrary to tumor tissue, MCF-7 cells do not express SULT1E1; steroid sulfation by this enzyme can be therefore excluded." (PMID 30042681, 2018). "In the same way, in breast cancer a high expression of SULT1E1 together with a decreased level of STS correlates with a better prognosis, smaller tumor size, and a negative lymph status at the time of diagnosis." (PMID 25429284, 2014).
infection (5 papers, 2011 to 2025). The state of being infected such as from the introduction of a foreign agent such as serum, vaccine, antigenic substance or organism. "Several of these genes are important in regulating oxidative stress to infection including Cyp2e1, aldehyde dehydrogenase (Aldh1a7) and sulphotransferase 1e1 (Sult1e1)." (PMID 21338512, 2011). "At the protein level, SULT1E1 was markedly elevated at 6 dpi of N10 infection." (PMID 39599894, 2024). "Collectively, these data indicated that Sult1e1 and Nrg4 are potential host response factors for DENV N10 strain infection." (PMID 39599894, 2024).
SULT1E1 also shares sentences with these, for which no sentence is quoted: endometriosis (4 papers); bladder cancer (2); glioblastoma (2); metabolic disorders (2); abortion (1); angiosarcoma of (1); brain neoplasm (1); chondrosarcoma (1); Cirrhosis (1); depression (1); diffuse large B-cell lymphoma (1); endometrial adenocarcinoma (1); endotoxemia (1); epilepsy (1); glioma (1); hemangioma (1); hepatoma (1); Lipedema (1); liver cancer (1); liver disease (1); male infertility (1); malignant meningiomas (1); Moyamoya disease (1); mucinous ovarian cancer (1); nutritional deficiency (1); paraganglioma (1); periodontitis (1); pheochromocytoma (1); relapsing-remitting multiple sclerosis (1); serous ovarian cancer (1).
A further 1 disease shares a sentence with SULT1E1 in 1 paper.